CD63 (CD63 molecule)
Diseases named in the same sentence as CD63 in open-access papers (continued):
Sharing a sentence is not in itself a finding about the gene and the disease.
diabetes (9 papers, 2015 to 2025). "The significant difference in baseline platelet surface expression of CD63 between the two groups underlines the fact that comorbid diabetes and depression can lead to serious vascular complications resulting from platelet hyperactivation." (PMID 35710773, 2022). "Elevated levels of platelets CD62P and CD63 have been described in people with type 1 and type 2 diabetes and were significantly higher in people with long-term complications of diabetes, such as diabetic nephropathy." (PMID 38139295, 2023). "The significant positive correlation of hs-CRP with CD63 elucidates the vicious cycle of diabetes leading to inflammation and vice versa." (PMID 35710773, 2022). "The expression of CD63 was high in patients with diabetes and depression compared to diabetes only group (p value < 0.001)." (PMID 35710773, 2022). "In fact, increased expression of CD63 and CD62, enhanced platelet activation, and aggregation are viewed as one of the major causes of atherosclerosis and thrombosis in diabetes." (PMID 27036108, 2016). "Other genes involved in obesity (e.g., Cidec, Cd36), diabetes (Igfbp1), inflammation (Cd63), mitochondrial function (Pdk4) and cancer (H19) were also upregulated by the soybean oil diet." (PMID 26200659, 2015). "Interestingly, CD63 exhibits high expression in patients with comorbid diabetes and depression compared to those with diabetes alone." (PMID 38812487, 2024). "Moreover, platelet degranulation is observed along with atherogenesis in diabetes mellitus, where correlation was found between increased platelet degranulation markers (CD63 and CD40L) and atherosclerosis progression." (PMID 28831120, 2017). "CD9, CD63, CD81, and CD41a expression progressively decreased in the Healthy, Diabetes, and DFU groups, respectively." (PMID 39835574, 2025). "Baseline assessments showed raised levels of CD31, CD49b, CD62P, and CD63 in the diabetes group when compared to the non-diabetes control." (PMID 38139295, 2023). "Post hoc analysis showed significantly high CD63 expression in patients with comorbid diabetes and depression compared to those having diabetes without depression." (PMID 35710773, 2022). "A study examining type 2 diabetes mellitus (T2DM) found significantly higher CD63 expression in T2DM individuals with comorbid depression compared to those with diabetes alone, suggesting that CD63 could serve as a potential biomarker for depression, particularly in individuals with comorbid T2DM." (PMID 40370590, 2025).
leukemia (8 papers, 2012 to 2025). A malignant (clonal) hematologic disorder, involving hematopoietic stem cells and characterized by the presence of primitive or atypical myeloid or lymphoid cells in the bone marrow and the blood. "The method captures leukemia-derived exosomes using anti-CD63 antibody-modified magnetic beads (MB-CD63), then triggers rolling circle amplification (RCA) with AS1411-containing DNA primers." (PMID 40699635, 2025). "To isolate blast-derived sEV from patients’ plasma, we developed a bioprinted microarray-based immunoassay using monoclonal antibodies (mAbs) specific for leukemia-associated antigens (LAAs) and mAbs specific for a mix of tetraspanins (CD9, CD63, and CD81)." (PMID 38137457, 2023). "They first modified magnetic bead conjugates with anti-CD63 antibodies (MB-CD63) to entrap leukemia-cell-derived exosomes containing CD63 and nucleolin." (PMID 36772521, 2023). "Both CD63 and nucleolin were used as targets to capture exosomes derived from leukemia cells using anti-CD63 antibody conjugated with magnetic beads." (PMID 34940275, 2021). "For the leukemia dataset, among the 10 top-ranked genes, two genes (ZYX and CCND3) are cancer ones, five (APLP2, CD33, SP3, CD63, PSME1) and one other genes (CST3) are directly or indirectly associated with cancer genes, respectively." (PMID 22830977, 2012).
lung adenocarcinoma (8 papers, 2018 to 2024). A carcinoma that arises from the lung and is characterized by the presence of malignant glandular epithelial cells. "Aberrant TIMP1 overexpression in cancer-associated fibroblasts stimulates tumor progression through CD63 in lung adenocarcinoma." (PMID 39769169, 2024). "In the human lung adenocarcinoma samples used in our study, the hybridization signals showed cytoplasmic localization and were detected in CD63-positive vesicles." (PMID 36635266, 2023). "In lung adenocarcinomas, low CD63 levels relative to normal lung tissue were significantly associated with poorer survival for patients with grade I and II disease, but not for grade III." (PMID 29523123, 2018). "The expression of α3 and β1 integrin subunits was found in exosomes isolated from the supernatant of 4 lung adenocarcinoma cell lines A549, H1975, H3255, and H1650 and a patient pericardial effusion by Western blots using exosomal (CD63) and cellular-specific (β-actin) markers." (PMID 31182116, 2019). "In lung adenocarcinoma cells, Tissue Inhibitor of Metalloproteinases-1 (TIMP-1) induces miR-210 upregulation through a CD63 Antigen (CD63)/PI3K/AKT/HIF-1-dependent pathway." (PMID 38612567, 2024). "Lung adenocarcinoma-derived exosomal miR-19b-3p (size range of 100 nm, marker proteins CD9, CD81) and miR-10b (bilayer membrane structure, typical “cupped” structure, marker proteins TSG101,CD63,CD81) facilitate macrophage polarization to the M2 type to promote lung adenocarcinoma development." (PMID 39165926, 2024). "With slight differences, the tetraspanin composition of CD63 positive sEV was alike in both lung adenocarcinoma cell-derived sEV populations, but not in 2106T cell-derived sEV." (PMID 35955677, 2022).
bladder cancer (7 papers, 2017 to 2025). "Thus, we isolated sEV from bladder cancer cells by differential centrifugation, and they displayed sphere-like morphology, diameter ~ 100 nm, high expression of CD63, Alix, and TSG101, and low expression of the ER-associated chaperone protein calnexin." (PMID 38561669, 2024). "The results of this proof‐of‐concept assay call for further clinical evaluation with more extensive and diverse patient material to clarify the clinical significance of CD63‐positive uEVs in the context of bladder cancer." (PMID 40625368, 2025). "Along with the high sensitivity for uEV detection, the CD63‐UCNP‐LFIA shows promise in distinguishing bladder cancer from benign and healthy individuals." (PMID 40625368, 2025). "Although prior studies have independently linked CD63+ or CD147+ EVs to therapy resistance, our results imply that the CD63+/CD147+ EV subpopulation is critically involved in GCB‐resistant bladder cancer." (PMID 41159684, 2025). "We found that both N-glycan signature and CD63 were highest in HG bladder cancer." (PMID 35265520, 2022). "Since this portion of EVs would less likely add clinically relevant diagnostic values for assessing the risks of bladder cancer, we excluded the use of DTT to remove THP from urine in the CD63-based microchip ELISA for analyzing urinary EVs derived from bladder cancer patients." (PMID 28436447, 2017). "Notably, the surrogate marker CD63 could distinguish low-COX7B subclones; thus, the authors speculated that COX7B and CD63 together contribute to platinum resistance in platinum-naïve bladder cancer." (PMID 36338973, 2022). "We selected generic exosome markers CD9, CD63, and TSG101, as well as the EDIL-3 and MUC4 for Western blotting analysis of urinary exosome proteins prepared by UC and NanoPoms methods, with the human bladder carcinoma cell line HTB9 as the control." (PMID 35787656, 2022). "Minimally processed uEV samples from bladder cancer (BlCa) (n = 62), benign prostatic hyperplasia (BPH) (n = 50) and healthy (n = 30) individuals were tested in sandwich UCNP‐LFIA format, capturing uEVs with the same anti‐CD63 antibody conjugated to UCNP and immobilized on the test zone." (PMID 40625368, 2025). "Sialic acid levels on CD63 were significantly lower in plasma from bladder cancer patients, accompanied by an elevated total CD63 level, suggesting that changes in sialic acids on sEV are not stem from the elevated sialylated CD63 in bladder cancer." (PMID 38561669, 2024).
oral cancer (7 papers, 2019 to 2023). "Oral fluids collected from oral cancer patients (n=36) and health individuals (n=25) was evaluated for amount of exosomal proteins CD63, CD9 and CD81." (PMID 38059133, 2023). "In oral cancer patients the exosomal pellets obtained from the oral fluids showed the presence of the glycosylated form of CD63 as a prominent band at 53Kd." (PMID 38059133, 2023). "Some scholars found that higher expression of miR-155, miR-21, miR-130a, CD63 and CAV1 in serum exosomes was associated with lower survival in oral cancer." (PMID 36768288, 2023). "More recently, label-free quantification was used to identify 415 proteins in CD63+/CD9+/TSG101+ EVs from the plasma of patients with oral cancer." (PMID 33158181, 2020). "Beyond this, a recent study demonstrated that CD63+/CD9+ EVs from the saliva of patients with oral cancers have unique and discriminatory infrared signatures compared with healthy controls." (PMID 33158181, 2020). "Only one study has compared EV levels from the plasma of patients with oral cancer before and after surgery and showed that certain subpopulations of EVs were decreased (CD63+) or increased (Calveolin-1+)." (PMID 33158181, 2020). "A higher expression of the CD63 molecule was observed in EVs from the saliva of patients with oral cancers in respect to normal subjects." (PMID 31247906, 2019). "Building on this, another study revealed that some miRNAs were exclusive (miR-302b-3p and miR-517b-3p) to CD63+/CD9+/Alix+/TSG101+ EVs from the saliva of patients with oral cancer compared with controls whereas others were up-regulated (miR-512-3p and miR-412-3p)." (PMID 33158181, 2020). "Interestingly, oral cancer exosomesexhibited significantly increased CD63 surface densities and displayed irregularmorphologies." (PMID 31496355, 2019). "Western blot can detect proteins CD63, Rab 5, CD9 and Alix in the exosomes derived from oral cancer patients." (PMID 38059133, 2023). "Despite CD63, CD81, and CD9 are downregulated in patients with oral cancer (OC)." (PMID 37304135, 2023). "Therefore, a significantly reduced level of CD9 and CD81 expression, rather than an ambiguous increase in CD63 expression, can be used as an indicator of oral cancer, even in the early stages of the disease." (PMID 36707844, 2023).
allergic asthma (6 papers, 2018 to 2025). A asthma with a basis in a pathological type I hypersensitivity reaction. "In contrast to other reports, we did not observe any significant changes in the surface markers such as CD203c and CD63 in our cohort of stable-mildly symptomatic allergic asthma patients." (PMID 36685514, 2022). "One study showed that PBdMC generated from healthy controls and patients with allergic asthma are very similar regarding degranulation measured by CD63 upregulation." (PMID 29992767, 2018).
breast tumors (6 papers, 2011 to 2023). "Data from other available resources such as Cancer Genome Atlas, or Protein Atlas, supported the notion that expression of CD63 in breast tumors is uncommon." (PMID 37081824, 2023). "CD63 is a widely used exosomal marker and its expression correlates with increased aggressiveness and metastatic potential of breast tumors." (PMID 27845903, 2016). "TIMP-1 and CD63 exhibited moderate to strong expression in 42% and 41%, respectively, of the breast tumors (respectively)." (PMID 22957045, 2012). "Consistent with the observations in 4T1/67NR mouse models, breast tumors with signatures of low CD81+CD63+EVs had a significantly higher frequency of M2 macrophages (known to differentiate from M-MDSCs) compared with tumors with signatures of high CD81+CD63+EVs." (PMID 34503207, 2021). "In order to follow their release and uptake in breast tumor cells in real time, cell-derived exosomes were tagged with green fluorescent protein (GFP)-CD63 while human serum exosomes were rhodamine isothiocynate-labeled." (PMID 21915303, 2011). "In human non-metastatic breast tumors, tumors enriched in signatures of CD81+CD63+EV have a better prognosis, higher immune cytolytic activity, and enrichment of pro-inflammatory macrophages compared with tumors with low CD81+CD63+EVs signatures." (PMID 34503207, 2021).
HCMV infection (6 papers, 2014 to 2024). "CD63, a marker for multivesicular bodies, appeared as dot-like structures, which were widely spread over the cytoplasm early in HCMV infection (24 hpi)." (PMID 24517969, 2014). "However, STING dimers were released during VZV and HCMV infections along with CD63 + EVs, as in HSV-1-infected cells, suggesting that STING exocytosis is common among herpesviruses despite a few exceptions." (PMID 38470056, 2024). "The peptide comprising the cytoplasmic C-terminal tail of CD151 significantly reduced HCMV infection rates in EA.hy926 and HEC-LTT cells, while the peptide of the cytoplasmic C-terminal tail of CD63 significantly decreased HCMV infection rates in all cell lines tested." (PMID 30279342, 2018). "We demonstrate that C-terminal peptides of CD63 and CD151 exhibit a moderate to potent inhibitory effect on HPV16 and HCMV infections." (PMID 30279342, 2018). "It has been shown that CD9, CD81 and CD151 were downregulated during HCMV entry and that cellular depletion of CD9, CD63 and CD151 reduced HCMV infection." (PMID 30279342, 2018). "More importantly, we show that cytopermeable peptides comprising the C-termini of CD63 and CD151 had a moderate to potent inhibitory effect on HPV16 and HCMV infections in different cell lines." (PMID 30279342, 2018). "Furthermore, we analyzed the involvement of specific tetraspanin domains, the LEL and the C-terminus, in HPV and HCMV infection by using recombinant peptides or proteins comprising these domains of CD9, CD63, CD81 and CD151 tetraspanins." (PMID 30279342, 2018). "In this study we compared the importance of tetraspanins CD9, CD63, CD81 and CD151 in infections by human papilloma- and cytomegalovirus and investigated whether peptides of functional tetraspanin domains could be used as inhibitors of HPV and HCMV infection." (PMID 30279342, 2018). "Hence, hCMV infection increased HIPEC-sEV production but did not globally impact on their global features, except for CD63 that is detected in a subpopulation of vesicles upon infection." (PMID 36146834, 2022).
Hepatic fibrosis (6 papers, 2014 to 2026). The presence of excessive fibrous connective tissue in the liver. "A subset of macrophages expressing SPP1, GPNMB, FABP5, and CD63 have also recently been identified in pulmonary and hepatic fibrosis associated with scar formation." (PMID 38902328, 2024). "TIMP1+ LSECs promote the recruitment of CD63+ monocyte-derived macrophages (MoMFs) during liver fibrosis progression." (PMID 41842990, 2026). "For example, Su and colleagues, revealed that EDA-FN secretion promoted VEGFR-2 recruitment to β1 integrin sites, upregulating VEGFR-2 phosphorylation and pathologic angiogenesis during hepatic fibrosis in a CD63-dependent manner." (PMID 36970722, 2022). "This study revealed that TM4SF5 levels were positively correlated with CD151 expression but were negatively with CD63 expression during liver fibrosis and tumorigenesis." (PMID 25033048, 2014). "We found that TM4SF5 expression could override CD151 functions, and TM4SF5 acted antagonistically to CD63 during liver fibrosis development and during hepatic migration/invasive extracellular matrix (ECM) -degradation." (PMID 25033048, 2014). "In addition, CD63 was highly expressed in the neovessel areas and colocalized with CD31 in mouse experimental liver fibrosis models." (PMID 33293521, 2020).
HIV-1 infection (6 papers, 2008 to 2021). The type species of lentivirus and the etiologic agent of acquired immunodeficiency syndrome (AIDS). "However, a significant inverse correlation was observed between surface CD63 and CD9 in SE and SE-mediated inhibition of HIV-1 infection in a pre-treatment infection model, where increased SE-CD63 or SE-CD9 content is associated with decreased HIV-1 infectivity (f respectively)." (PMID 28338013, 2017). "Since cell–cell spread of HIV-1 is a major route of persistent infection, these results highlight the central role of CD63 as a member of the tetraspanin superfamily during HIV-1 infection and pathogenesis." (PMID 33976357, 2021). "Another explanation could be, as it was shown in previous work, that HIV infected T cells are resistant to inhibition of HIV-1 infection by a CD63 antibody, but sensitive to CD63 down regulation by siRNA." (PMID 19284574, 2009). "Similarly, it has been suggested that the tetraspanin CD63 plays a role in the entry process of HIV-1 as it has recently been reported that HIV-1 infection was inhibited by anti-CD63 antibodies and also by recombinant soluble forms of the large extracellular domain of human tetraspanins." (PMID 18836553, 2008). "For example, a correlation between HIV-1 infection and acetylcholine-esterase, CD9 and CD63 exosome surface protein levels is observed in different models of infection, and increased protein levels are correlated with decreased HIV-1 infectivity." (PMID 30702421, 2019).
Myocardial fibrosis (6 papers, 2019 to 2026). "Of interest, a recent study has shown that TIMP1 deficiency have significantly reduced myocardial fibrosis via meditating an association between CD63 (cell surface receptor for TIMP1) and integrin β1 on CFs, leading to de novo collagen synthesis, reducing myocardial fibrosis, independent from MMPs." (PMID 40843168, 2025). "TIMP1 was shown to induce myocardial fibrosis through mediating an interaction between fibroblast membrane proteins, CD63, and integrin β1." (PMID 31141909, 2019). "TIMP1 promotes myocardial fibrosis through a novel mechanism involving CD63‐integrin β1 interaction, independent of its MMP‐inhibitory function." (PMID 41521401, 2026). "Through CD63 (TIMP1 cell-surface receptors), TIMP1 and integrin beta 1 could promote activation and nuclear transfer of Smad2/3 and the beta serial protein, resulting in the deposition of types I and III collagen and subsequently myocardial fibrosis." (PMID 38728374, 2024).
Obesity (6 papers, 2015 to 2025). Accumulation of substantial excess body fat. "Serum levels of EV markers CD9/CD63 and sonic hedgehog N-terminal (Shh-N) were significantly higher in adolescents with obesity compared to both healthy controls and those with T2D." (PMID 41150813, 2025). "To determine whether our findings generated from obese HFD-fed mice are applicable in patients with obesity-induced T2D, we isolated CD63+A33+ exosomes from the stool samples of healthy and obese individuals and patients with T2D." (PMID 33754048, 2021). "The alteration in the PLIN3/CD63 ratio may thus occur during an early or metabolically dysregulated stage of MASLD independent of obesity." (PMID 41295331, 2025). "In lean MASLD, metabolic stress in the absence of overt obesity may promote lipid droplet remodeling or impair vesicular trafficking, leading to reduced PLIN3 incorporation into EVs relative to CD63." (PMID 41295331, 2025).